CCL7 (C-C motif chemokine ligand 7)
Diseases named in the same sentence as CCL7 in open-access papers (continued):
Sharing a sentence is not in itself a finding about the gene and the disease.
fibrosis (7 papers, 2016 to 2025). the formation of excess fibrous connective tissue in an organ or tissue in a reparative or reactive process. "Mice with lung epithelial cell-specific deletion of Ccl12 are protected from bleomycin-induced fibrosis, showing decreased macrophage recruitment with Ccl2 and Ccl7 expression similar to control mice." (PMID 39768150, 2024).
gastric cancer (7 papers, 2014 to 2025). A primary or metastatic malignant neoplasm involving the stomach. "CCL7 has been found to be overexpressed in gastric cancer tissues and is associated with tumor lymph node metastasis and poor prognosis." (PMID 25193015, 2014). "Furthermore, CCL7 overexpression was associated with lymph node metastasis and poor prognosis in gastric cancer." (PMID 30764543, 2019). "More adipose inflammatory factors can be released by CAAs in gastric cancer, indirectly increasing CCL7 production." (PMID 29915688, 2018). "Similarly, it was also reported that CCR1 involved CCL7-induced liver metastasis of CRC as well as gastric cancer metastasis." (PMID 35715847, 2022). "CCL7 expression is higher and more pronounced in the cytoplasm of gastric cancer cells than matched adjacent non-neoplastic tissues." (PMID 29915688, 2018).
liver disease (7 papers, 2010 to 2024). "These chemokines such as CCL2, CCL7, CCL8, CCL11 and CCL12 were demonstrated as pro-fibrosis cytokines in liver diseases and highly expressed during our murine schistosomiasis model, and reduced more or less after PZQ treatment." (PMID 22905138, 2012). "The induction of CCL7 and CCL12 during fibrosis is consistent with the role of the related chemokine CCL2 in other liver diseases." (PMID 20161726, 2010). "Although a variety of chemokines have been well studied in various diseases, there is no comprehensive review presenting the roles of all known chemokine ligands of CCR2 (CCL2, CCL7, CCL8, CCL12, CCL13, CCL16, and PSMP) in liver disease, and this review aims to fill this gap." (PMID 35281057, 2022). "However, other ligands of CCR2 have not been thoroughly studied in liver diseases, especially CCL7, CCL8, CCL12, CCL13, CCL16, and PSMP." (PMID 35281057, 2022).
acute kidney injury (6 papers, 2020 to 2024). Sudden and sustained deterioration of the kidney function characterized by decreased glomerular filtration rate, increased serum creatinine or oliguria. "Previous studies demonstrated the relationships between CCL7 and various kidney diseases, such as acute kidney injury, renal fibrosis, kidney stone, and end-stage renal disease (ESRD)." (PMID 38235001, 2023). "In response to acute kidney injury, B cells produce CCL7 to facilitate neutrophil and monocyte recruitment to the injured sites." (PMID 36109744, 2022). "In another study on acute kidney injury, the researchers also found that B cells produced chemokine CCL7, with the potential to facilitate neutrophil and monocyte recruitment to the injured kidney, aggravating renal impairment." (PMID 35350762, 2022). "CCL7 blockade in mice markedly reduced myeloid cell infiltration into the kidney and ameliorated acute kidney injury." (PMID 35350762, 2022). "And in human kidney biopsy specimens, CCL7 transcript levels were significantly higher in AKI kidneys than in kidneys with normal renal function, further demonstrating that B cells and CCL7 levels correlate with the degree of acute kidney injury." (PMID 38022595, 2023).
Hypertension (6 papers, 2019 to 2024). The presence of chronic increased pressure in the systemic arterial system. "CCL7 inhibition with antibodies can attenuate angiotensin-II-induced hypertension and vascular remodeling, accompanied by decreased macrophage infiltration." (PMID 36109744, 2022). "It is important to note that neutralizing CCL7 significantly alleviated Ang II-induced hypertension and vascular remodeling in vivo." (PMID 31320613, 2019). "Blocking CCL7 with antibody in vivo alleviated Ang II-induced hypertension and vascular remodeling, coincident with decreased macrophage infiltration." (PMID 31320613, 2019). "Moreover, CCL7 blockade attenuated Ang II-induced hypertension and vascular remodeling in vivo, indicating that HIF1α or CCL7 blockade may be a potential means for treating vascular remodeling disease." (PMID 31320613, 2019). "In a deoxycorticosterone acetate/salt-induced hypertension mouse model, mRNA expression of CCR2 and its ligands, such as CCL2, CCL7, CCL8, and CCL12, in the aorta was upregulated." (PMID 36109744, 2022). "Myocardial stress, such as pressure overload or salt-induced hypertension, drives upregulation of CCR2 ligands, such as monocyte chemotactic protein-1 (MCP-1 or CCL2), MCP-3 (or CCL7), CCL12, and SDF-1alpha, which play an essential role in CCR2+ monocyte influx into the heart." (PMID 31963368, 2020).
melanoma (6 papers, 2006 to 2025). A malignant, usually aggressive tumor composed of atypical, neoplastic melanocytes. "In the attempt to elucidate the factors involved in this process, we identify CCL7 as one of the chemokines secreted by GLI1-silenced melanoma cells." (PMID 39090759, 2024). "Overexpression of GLI1 in A375 melanoma cells drastically downregulated CCL7, CCL2, CCL20 and CXCL8 mRNA level." (PMID 39090759, 2024). "Our PCR array analysis indicates that expression of three genes such as CCL7, Gdf 5 and interleukin 8rα was detected only in T+ and T++ melanoma clones." (PMID 26197340, 2015). "Altogether, these data suggest a tumor suppressive role of CCL7 in melanoma." (PMID 39090759, 2024). "Cytokine array from SSM2c cells transduced with LV-c or LV-shGLI1 showed a significantly higher secretion of CCL7, CCL2, CCL20 and CXCL8 (IL-8) in CM collected from GLI1-silenced melanoma cells." (PMID 39090759, 2024). "In addition, our study allows the identification of an immunosuppressive signature characterized by high GLI and low cytokine/chemokine expression (CCL7, CCL2, CCL20, CXCL8, CXCL1 and CXCL10), which could be used to stratify melanoma patients with poor survival." (PMID 39090759, 2024).
neuropathy (6 papers, 2016 to 2025). A disorder affecting the nervous system that manifests with pain, tingling, numbness, and/or muscle weakness. "Published data indicate that the long-lasting upregulation of CCL7 induced by nerve injury is associated with enhanced multidirectional spinal communication between neurons, microglia, and astrocytes, which leads to sensory neuron sensitization in the early and late phases of neuropathy." (PMID 37570736, 2023). "Our results indicate that this chemokine participates in the initialization and maintenance of neuropathic pain after nerve ligation because enhanced CCL7 mRNA/protein levels were observed between the 2nd and 28th days of neuropathy." (PMID 36611891, 2022). "The results confirmed that CCL7 is strongly involved in the development of hypersensitivity in neuropathy." (PMID 32691345, 2020). "Importantly, from a clinical point of view, neutralization of CCL7 by its antibody was able to decrease pain-like behaviors in the model of neuropathy." (PMID 36611891, 2022). "CCL7 may be released from macrophages, neurons and astrocytes and can evoke chemotaxis or activation of other cells, e.g., microglia, macrophages and neutrophils, which are known to be important in neuropathy." (PMID 36611891, 2022). "Among them, CCL7 and CCL8 are the common ligands of both receptors with well-known long-lasting increases and strong pronociceptive properties in neuropathy." (PMID 37570736, 2023). "Moreover, neutralization of chemokines (e.g., CCL2, CCL3, CCL4, CCL7, and CXCL1) may reduce hypersensitivity and the inflammatory response in animal models of neuropathy." (PMID 34795678, 2021).
ovarian carcinoma (6 papers, 2015 to 2023). A malignant neoplasm originating from the surface ovarian epithelium. "Here, we found that CCL7 upregulation in macrophages stimulated by the CM of ovarian cancer cells was associated with the p38/JNK pathway." (PMID 34206004, 2021). "The expression of MMP-9, but not MMP-2, was associated with ERK activation and cancer invasion by CCL7 in human ovarian cancer cells." (PMID 34206004, 2021). "A decrease in IL-2, MCP-2/CCL8 and MCP-3/CCL7 levels was detected in both ovarian cancer cell lines with leptin administration." (PMID 37155466, 2023). "Our research shows that exosomes from ovarian cancer cells lead to an increase in the expression of CCL7 in fibroblasts." (PMID 36012171, 2022). "CCL7 from OC-MQs, which mimic TAMs, promoted ovarian cancer cell migration and invasion through the CCR3-ERK pathway." (PMID 34206004, 2021). "Together, these data indicate that CCL7 overproduction from macrophages stimulated by cancer cells increases the invasion of ovarian cancer cells by regulating MMP-9 via the ERK pathway." (PMID 34206004, 2021). "Inhibition of CCL7 using siRNA and neutralizing antibodies reduced the OC-MQ-CM-induced ovarian cancer cell invasion." (PMID 34206004, 2021). "Neutralizing anti-CCL7 antibodies significantly suppressed the invasion of ovarian cancer cells stimulated by A-MQ and O-MQ." (PMID 34206004, 2021). "Together, these data suggest that macrophages stimulated by cancer cells produce high levels of CCL7, which can play a role in human ovarian cancer invasion." (PMID 34206004, 2021). "The upregulation of CCL7 in macrophages stimulated with the CM of ovarian cancer cells (both A2780-CM and OVCAR3-CM) was significantly negated by the p38 inhibitor, SB203580, and the JNK inhibitor, SP600125." (PMID 34206004, 2021). "Given that the ERK signaling pathway is associated with the migration and invasion of malignant tumors and CCL7-associated pro-cancer activities, we investigated the role of ERK signaling in CCL7-induced ovarian cancer cell invasion." (PMID 34206004, 2021). "We found that OC-MQ produced a large amount of the CC subfamily chemokine, CCL7, compared to control macrophages, and the levels of CCL7 were significantly enhanced in peritoneal macrophages of patients with ovarian cancer." (PMID 34206004, 2021). "In the current study, we demonstrated that CCL7 derived from macrophages stimulated the invasion and migration of ovarian cancer cells via CCR3." (PMID 34206004, 2021). "The CCL7-stimulated increase in ovarian cancer cell invasion was significantly reduced in the presence of PD98059." (PMID 34206004, 2021). "CCL7-induced invasion required the expression of matrix metalloproteinase 9 via activation of extracellular signal-related kinase signaling in human ovarian cancer cells." (PMID 34206004, 2021). "Peritoneal macrophages from patients with ovarian cancer showed higher CCL7 expression levels than those from healthy controls." (PMID 34206004, 2021). "Moreover, the p38/JNK pathways seem to be involved in histone lysine demethylase PHF8-mediated CCL7 expression in macrophages stimulated by ovarian cancer cells." (PMID 34206004, 2021). "In addition, we found that ERK activation and MMP-9 expression were required for ovarian cancer cell migration by CCL7." (PMID 34206004, 2021). "We investigated whether CCL7 secreted from OC-MQ directly contributed to the invasion of human ovarian cancer cells." (PMID 34206004, 2021). "Considering the well-characterized role of MMP-9 and MMP-2 in the metastases of many cancers, including ovarian cancer, we investigated whether CCL7-induced ERK activation mediated the expression of these enzymes." (PMID 34206004, 2021). "Similarly, knockdown of CCL7 in macrophages using a specific siRNA resulted in significant suppression of ovarian cancer cell invasion." (PMID 34206004, 2021).
ovarian carcinoma (continued). "In our study, we observed an increase in the expression of VEGFA and three cytokines (IL18, CCL7 and CXCL12) in fibroblasts after treatment with exosomes derived from ovarian cancer cells." (PMID 36012171, 2022). "The results indicate significant changes in the expression of both CCL7 and CXCL12 in fibroblasts after treatment with exosomes derived from ovarian cancer cells." (PMID 36012171, 2022). "We further evaluated the effect of ERK activation by CCL7 on the expression of MMP-2 and -9, which play critical roles in ovarian cancer metastasis." (PMID 34206004, 2021). "Together, these data suggest that CCR3 in human ovarian cancer cells can be stimulated by CCL7 from TAMs, as well as CCL5 and CCL11, and can play a critical role in ovarian cancer metastasis." (PMID 34206004, 2021). "In this study, we demonstrated that CCL7 from macrophages stimulated by ovarian cancer cells increased ovarian cancer cell invasion and migration, suggesting that TAM-derived CCL7 is a key factor for ovarian cancer metastasis." (PMID 34206004, 2021). "Ovarian cancer cells have been shown to express the canonical monocyte recruitment factors, CCL2 and CCL7." (PMID 33069212, 2020). "Consequently, our results demonstrated the pro-malignant role of the CCL7/CCR3 axis and suggested that targeting this axis could be an effective method to inhibit the metastatic spread of ovarian cancer cells by regulating the tumor microenvironment." (PMID 34206004, 2021). "In addition, IOSE80PC-MQ, from macrophages stimulated by normal ovarian surface epithelial cells (IOSE80PC), showed no increase in CCL7 production or mRNA expression, indicating that macrophages stimulated by ovarian cancer cells, but not their normal counterpart, can highly produce CCL7." (PMID 34206004, 2021).
periodontitis (6 papers, 2014 to 2024). An acute or chronic inflammatory process that affects the tissues that surround and support the teeth. "Moreover, PRF membranes increased chemokines CCL2, CCL7, CXCL2, and CXCL3, most of which are highly expressed in periodontitis fibroblasts." (PMID 39120336, 2024). "Indeed, high levels of CCL11, also named Eotaxin-1/C-C motif chemokine 11, CXCL12, also referred to as stromal cell-derived factor-1 (SDF-1) and CCL7, also known as monocyte chemotactic protein-3 (MCP-3) were suggested as biomarkers for periodontitis." (PMID 35048045, 2021).
psoriasis (6 papers, 2017 to 2026). An autoimmune condition characterized by red, well-delineated plaques with silvery scales that are usually on the extensor surfaces and scalp. "Dysregulated CCL7 is implicated in, and worsens, immunological diseases, including MS and psoriasis, against which DMF is particularly effective." (PMID 37751291, 2023). "CCL11 is upregulated in atopic dermatitis while CCL7 is increased in psoriasis and sclerosis where they are thought to promote skin inflammation and fibrosis." (PMID 37228128, 2023). "Chemokines such as CCL20 and MCP-3/CCL7 are stimulated by Th17 cell cytokines, e.g., IL-17A, which may contribute to a positive IL-17 response feedback loop in psoriasis." (PMID 35008981, 2022). "These include proinflammatory chemokines common to AD and psoriasis, namely CCL2, CCL5 and CCL7, that mediate recruitment of monocytes, T cells, and eosinophils." (PMID 28530223, 2017). "We confirmed that endogenous TWEAK was required for maximal expression of CCL2, CCL5 and CCL7, and furthermore, we found defective production of CCL17 and CCL20 in mice lacking TWEAK in the AD model and the psoriasis model, respectively." (PMID 28530223, 2017).
acute respiratory distress syndrome (5 papers, 2017 to 2024). Progressive and life-threatening pulmonary distress in the absence of an underlying pulmonary condition, usually following major trauma or surgery. "As it has been shown that CXCL13 and CCL21 have synergistic effects in lymphoid tissue production in RA synovitis and more recently that CCL7 has been shown to synergise with CXCL8 in acute respiratory distress syndrome to promote neutrophil migration." (PMID 28648867, 2017). "Also, CCL2 and CCL7 chemokines are known to work synergistically with CXCL8 to drive neutrophil trafficking to the lungs during acute respiratory distress syndrome (ARDS)." (PMID 34737734, 2021). "A recent study reported that in acute respiratory distress syndrome (ARDS), CCL2, and CCL7 synergize with CXCL8 to promote neutrophil migration." (PMID 29018439, 2017).
encephalitis (5 papers, 2013 to 2025). An acute inflammatory process affecting the brain parenchyma. "Compared to MCP-1-deficient mice, CCL7-deficient mice showed less infiltration of monocytes in the encephalitis model caused by West Nile virus infection, which indicates that CCL7 has a stronger chemotactic activity than that of MCP-1." (PMID 29743924, 2018). "CCL2 mRNA was upregulated in cultured astrocytes, but remained at low levels compared to CCL7, suggesting a role for CCL7 in HIV-related encephalitis." (PMID 23997430, 2013). "That CCL7 is upregulated by astrocytes in response to cytokines present in encephalitic brains gives a potential role for controlling monocyte migration during encephalitis as well." (PMID 23997430, 2013). "Expression of CCL3, CCL5, CCL7 and CCL19 chemokines could play a crucial role in recruitment of IFN-γ-producing CD8+ T cells into the brain, and in facilitating migration of effector macrophages for prevention of Toxoplasma encephalitis during acute stage of encephalitis." (PMID 23374751, 2013).
experimental autoimmune encephalomyelitis (5 papers, 2015 to 2023). An autoimmune demyelinating disease of the central nervous system that is produced experimentally in animals by the injection of homogenized brain or spinal cord in Freund's adjuvant. "Moreover, the upregulation of Ccl2, Ccl3, Ccl4, Ccl7, Cxcl9, and Cxcl10 is also related to the acute phase of experimental autoimmune encephalomyelitis." (PMID 35911717, 2022). "In addition, animal experiments revealed that leukocyte migration in experimental autoimmune encephalomyelitis could be inhibited by targeting MCP-3/CCL7 thereby preventing disease progression." (PMID 38173728, 2023). "As XPro1595 has previously been shown to decrease CCL7 levels in the spinal cord of mice with experimental autoimmune encephalomyelitis (EAE) and these mice are protected from EAE, we studied the effect of selective solTNF inhibition on the temporal Ccl7 expression." (PMID 37372129, 2023). "CXCL10/IP-10, CCL2/MCP-1, CCL3/MIP-1a, CCL4/MIP-1b, CCL5/Rantes, CCL7/MCP-3 and CXCL9/Mig are among the described proinflammatory chemokines produced by immune cells and CNS glia in MS and in the animal model of MS, experimental autoimmune encephalomyelitis (EAE)." (PMID 26039252, 2015).
lung adenocarcinoma (5 papers, 2020 to 2024). A carcinoma that arises from the lung and is characterized by the presence of malignant glandular epithelial cells. "Another study conducted by Wu and colleagues revealed that in lung adenocarcinoma tissues, higher CCL7 expression was associated with increased TAM tissue infiltration and CCL7 knockdown resulted in suppressed migration and M2 polarization of macrophages." (PMID 38372877, 2024). "Mesenchymal properties and mobility of lung adenocarcinoma cells were repressed following CCL7 knockdown representing TAMs as EMT inducers." (PMID 38372877, 2024). "Analysis of seven databases of lung adenocarcinoma (LUAD) integrated by Timer 2.0 illustrated that the CCL7 expression level positively correlated with the infiltration of macrophages including M0, M1 and M2 phases in six databases." (PMID 37161570, 2023). "This research studies the function of C-C motif chemokine ligand 7 (CCL7) in the macrophage accumulation in lung adenocarcinoma (LUAD) and the underpinning mechanism." (PMID 36118415, 2022). "LINC01094 increased the expression of CCL7 in lung adenocarcinoma by binding to the transcription factor SPI1 of CCL7 and promoting its translocation into the nucleus, thus increasing the degree of infiltration of macrophages in lung adenocarcinoma." (PMID 37637063, 2023).
myocarditis (5 papers, 2013 to 2025). Myocarditis is a condition that is characterized by inflammation of the heart muscle (myocardium). "This peptide inhibits the inflammatory chemokines CCL2, CCL3, CCL7, and CCL8 in murine Coxsackievirus B3 (CVB3) infection, a viral trigger of myocarditis." (PMID 40009121, 2025).